PLPPR5 (phospholipid phosphatase related 5)
Description:
Induces filopodia formation and promotes neurite growth in a CDC42-independent manner; impedes neurite growth inhibitory-mediated axonal retraction.
Synonyms: LPPR5; PAP2D; PRG5; PAP2
Tractability: Antibody: UniProt places it where antibodies can reach, with medium confidence; UniProt predicts a signal peptide or a membrane-spanning region; its Gene Ontology location is reachable by antibodies, with medium confidence; the Human Protein Atlas places it where antibodies can reach. PROTAC: its protein half-life has been measured.
Gene: Protein-coding gene on chromosome 1 (98,890,245 to 99,227,929, reverse strand). Ensembl gene ENSG00000117598.
Subcellular location: Cell membrane
Subcellular location (Human Protein Atlas): Plasma membrane; Cytosol
Pathways (Reactome):
Signal Transduction: Lysosphingolipid and LPA receptors
Gene Ontology:
Biological process: phospholipid dephosphorylation; phospholipid metabolic process; positive regulation of filopodium assembly; positive regulation of neuron projection development; signal transduction
Cellular component: plasma membrane
Genetic constraint (gnomAD): Loss-of-function variants: 14 observed, 31.16 expected, observed/expected ratio (o/e) 0.45, 90% interval 0.3 to 0.7. The upper end of that interval is the gene's LOEUF score, 0.7, which puts it in group 2 of 6, group 1 being the genes least tolerant of losing a copy. Missense variants: 294 observed, 412.38 expected, observed/expected ratio (o/e) 0.71, 90% interval 0.65 to 0.79. Synonymous variants: 159 observed, 153.25 expected, observed/expected ratio (o/e) 1.04, 90% interval 0.91 to 1.18.
Homologues: Orthologues: chimpanzee PLPPR5 (100% identical), pig PLPPR5 (95% identical), rabbit PLPPR5 (95% identical), guinea pig PLPPR5 (93% identical), rat Plppr5 (93% identical), mouse Plppr5 (92% identical), dog PLPPR5 (91% identical), macaque PLPPR5 (91% identical), tropical clawed frog plppr5 (81% identical), zebrafish plppr5b (70% identical), zebrafish plppr5a (66% identical), Drosophila melanogaster CG11437 (22% identical), and 8 more. Paralogues in human: PLPPR1 (54% identical), PLPPR2 (48% identical), PLPPR3 (35% identical), PLPPR4 (34% identical), PLPP3 (23% identical), PLPP1 (23% identical), PLPP2 (20% identical), PLPP4 (16% identical), PLPP5 (14% identical).
Diseases named in the same sentence as PLPPR5 in open-access papers:
PLPPR5 is named in the same sentence as 15 diseases in open-access papers, as found by Europe PMC text mining. Sharing a sentence is not in itself a finding about the gene and the disease. The quoted sentences say what the papers report.
neuroblastoma (2 papers, 2022). Neuroblastoma (NB) is the most common solid, extracranial childhood tumor. "Overexpression of PLPPR5 promotes the formation of plasma membrane protrusions in P19 carcinoma and N1E-115 neuroblastoma cells, as well as in cortical and hippocampal neurons." (PMID 36187351, 2022). "Furthermore, super resolution microscopy of co-overexpressed PLPPR1 and PLPPR5 or PLPPR3 showed both puncta formation at the plasma membrane in neuroblastoma cell lines." (PMID 36187351, 2022).
cerebral infarction (1 paper, 2022). An ischemic condition of the brain, producing a persistent focal neurological deficit in the area of distribution of the cerebral arteries. "Plppr5-deficient mice subjected to hypoxia-ischemia at postnatal day 10 present significantly higher cerebral infarction." (PMID 35401091, 2022).
epilepsy (1 paper, 2022). A brain disorder characterized by episodes of abnormally increased neuronal discharge resulting in transient episodes of sensory or motor neurological dysfunction, or psychic dysfunction. "Although the experimental approach differs markedly from the PLPPR4 studies described in the previous paragraph, PLPPR5 KO mice were found to be more prone to epilepsy with a lower seizure latency compared to WT mice." (PMID 36187351, 2022). "PLPPR5, which is positioned on the same chromosome region within 300 kb distance from the PLPPR4 gene in humans and rodents, has also been associated with epilepsy, albeit in a drug-induced animal model." (PMID 36187351, 2022).
PLPPR5 also shares sentences with these, for which no sentence is quoted: cancer (2 papers); cerebral palsy (2); glioma (2); brain injury (1); brain tumors (1); breast tumors (1); glioblastoma (1); hippocampal atrophy (1); lung carcinoma (1); neoplasia (1); neural tumors (1); oligodendroglioma (1).